TARDBP (TAR DNA binding protein)
Diseases named in the same sentence as TARDBP in open-access papers (continued):
Sharing a sentence is not in itself a finding about the gene and the disease.
type 2 diabetes (4 papers, 2021 to 2025). "Ci-Ins2 and its human ortholog ci-INS are downregulated in type 2 diabetes, predominantly localized in the nucleus, and interact with TARDBP." (PMID 34449657, 2021). "Hence, ci-Ins2 has an essential role in insulin secretion through sponging of the RNA binding protein TARDBP and is partly responsible for a defect in insulin secretion in the case of type II diabetes." (PMID 34449657, 2021).
Apathy (3 papers, 2023 to 2025). Apathy is a quantitative reduction of interest, motivation and the initiation and persistence of goal-directed behavior, where often the accompanying emotions, thoughts, and social interactions are also diminished. "Notably, apathy has been reported in ALS patients who have TARDBP mutations." (PMID 40856010, 2025).
Enterovirus infection (3 papers, 2021 to 2025). "Also, knockdown of TARDBP increases viral replication in macrophages and TDP-43 knockdown amplifies enterovirus infections, suggesting an antiviral effect of TDP-43." (PMID 38693436, 2024).
Ewing sarcoma (3 papers, 2018 to 2023). A small round cell tumor that lacks morphologic, immunohistochemical, and electron microscopic evidence of neuroectodermal differentiation. "The 1p36.22 variants associated with Ewing's sarcoma are located 25 kb proximal to the TARDBP gene." (PMID 29719630, 2018). "The involvement of TDP-43 in cancer was identified as early as two decades ago, with notable associations found between common variants near TARDBP and EGR2 and the incidence of Ewing sarcoma." (PMID 37996849, 2023).
Hyperglycemia (3 papers, 2018 to 2025). An increased concentration of glucose in the blood. "An interesting facet of this pathway was its feed-forward nature, whereby hyperglycemia led to enhanced activity of OGT, which in turn led to elevated OGT expression via the splicing factor TARDBP." (PMID 37231419, 2023).
Insulin resistance (3 papers, 2019 to 2025). Increased resistance towards insulin, that is, diminished effectiveness of insulin in reducing blood glucose levels. "As another explanation, T2D was recently reported to be associated with higher concentrations of progranulin, which could mediate fat-induced insulin resistance and revert mutant TDP-43 (TAR DNA-binding protein 43)-induced axonopathy." (PMID 31796040, 2019).
latent infection (3 papers, 2020 to 2024). "On the other hand, suppressors of viral transcription, such as TARDBP, which inhibits viral transcription by binding to the HIV-1 TAR element, were increased (1.7-fold) in latent infection." (PMID 38038477, 2023).
lysosomal storage disorder (3 papers, 2016 to 2024). "Lysosomes hold potential as an attractive target for therapeutic intervention in ALS, as in addition to VCP, several other ALS associated genes have a role in lysosomal homeostasis (C9orf72, TARDBP, TMEM106B, TBK1, OPTN, SQSTM1) and several lysosomal storage diseases manifest neurological features." (PMID 39593143, 2024).
vacuolar myopathies (3 papers, 2012 to 2024). "Furthermore, we investigated accumulation of TAR-DNA-binding protein-43 (TDP-43), a pathological hallmark of vacuolar myopathies, in the muscle fibers of DMRV/hIBM patients." (PMID 22540328, 2012).
Adult onset (2 papers, 2022). Onset of disease manifestations in adulthood, defined here as at the age of 16 years or later. "We report a patient with JALS and a pathogenic variant in the TARDBP gene (c.1035C > G; p.Asn345Lys), previously reported only in adult-onset ALS, and with an atypical phenotype of marked upper motor neuron predominance." (PMID 36011394, 2022).
autoimmune disease (2 papers, 2018 to 2021). A disorder resulting from loss of function or tissue destruction of an organ or multiple organs, arising from humoral or cellular immune responses of the individual to their own tissue constituents. "Vice versa a correlation between autoimmune diseases and Tar DNA-binding Protein 43 (TDP-43) mediated neurodegeneration in FTD patients has been reported." (PMID 30283395, 2018).
brain tumor (2 papers, 2017 to 2023). "Alterations in RBP expression levels and function have been associated with neurological disorders (e.g. HNRNPA1, MATR3, TIA1, and TARDBP and brain tumour development (e.g. Musashi1, SERBP1, PTB and HuR." (PMID 37294214, 2023).
Chorea (2 papers, 2016 to 2023). Chorea (Greek for 'dance') refers to widespread arrhythmic involuntary movements of a forcible, jerky and restless fashion. "A patient with a K263E TARDBP mutation developed FTD, supranuclear palsy, and chorea, but not ALS, which was associated with TDP-43 accumulation predominantly in subcortical nuclei and the brainstem." (PMID 27044537, 2016).
cortical atrophy (2 papers, 2022 to 2025). "Available data in the literature only included description of cortical atrophy by visual inspection of conventional MRI sequences, without displaying quantitative information on GM volumes or any information at all on WM alterations of patients affected by TARDBP mutations." (PMID 35911889, 2022).
gastric cancer (2 papers, 2024). A primary or metastatic malignant neoplasm involving the stomach. "Indeed, correlation analysis in gastric cancer patients from TCGA revealed a strong association in the expression of the two genes, suggesting that the regulation axis between TARDBP and ADAR could be functional in gastric cancer as well." (PMID 38773080, 2024).
influenza (2 papers, 2018 to 2024). An acute viral infection of the respiratory tract, occurring in isolated cases, in epidemics, or in pandemics; it is caused by serologically different strains of viruses (influenzaviruses) designated A, B, and C, has a 3-day incubation period, and usually lasts for 3 to 10 days. "TARDBP functions in negative regulation by host of viral transcription (GO biological process) and was previously implicated as part of the influenza-host interactome using human and mammalian cell lines in vitro." (PMID 30177951, 2018). "They showed that TDP-43, encoded by the TARDBP gene, binds several influenza mRNAs in addition to NP-mRNA, and that its depletion results in lower levels of viral mRNAs and proteins in infected cells and a reduced yield of infectious viral particles." (PMID 39795871, 2024).
intracerebral hemorrhage (2 papers, 2018 to 2022). A cerebrovascular disorder characterized by bleeding into one or both cerebral hemispheres including the basal ganglia and the cerebral cortex. "This study aimed to determine the role of TAR DNA binding protein-43 (TDP-43) in intracerebral hemorrhage (ICH)-induced secondary brain injury (SBI) and its underlying mechanisms." (PMID 29623031, 2018).
Nasu-Hakola disease (2 papers, 2020 to 2023). "In patients diagnosed with AD we found three C9orf72 expansions, nine DVs in MAPT, five in CSF1R, two in GRN, three in PRNP and one each in SQSTM1, TARDBP and VCP, as well as a homozygous TREM2 DV normally associated with Nasu-Hakola disease." (PMID 30279455, 2020).
acute lymphoblastic leukemia (1 paper, 2025). Leukemia with an acute onset, characterized by the presence of lymphoblasts in the bone marrow and the peripheral blood. "A recent discovery has highlighted a connection between acute lymphoblastic leukemia (ALL) and the trans-activation response DNA-binding protein (TARDBP)." (PMID 41228239, 2025).
acute myelogenous leukemia (1 paper, 2022). "RBM25, TARDBP, and CELF1 were found to be correlated with many CASEs, among which RBM25 was thought to inhibit the progression of acute myelogenous leukemia by affecting MYC activity." (PMID 35126520, 2022).
allergic asthma (1 paper, 2025). A asthma with a basis in a pathological type I hypersensitivity reaction. "Other identified genes, such as TARDBP, TENT4B, and HNRNPL, have not been previously implicated in allergic asthma." (PMID 40504147, 2025).
Camptocormia (1 paper, 2022). An abnormal forward-flexed posture e.g. forward flexion of the spine, which is noticeable when standing or walking but disappears when lying down. "Such heterogeneity diverges from previous reports, in which TARDBP mutations with MND have been mostly associated with an ALS syndrome, with the exception of one case of PMA, in a patient whose first symptom was camptocormia." (PMID 35911889, 2022).
cystic fibrosis (1 paper, 2023). Autosomal recessive disorder caused by pathogenic variants in the CFTR gene (cystic fibrosis transmembrane conductance regulator), which encodes a chloride and bicarbonate channel expressed in epithelial cells, and follow the diagnosis criteria. "Putative links between ALS and cystic fibrosis have been noted previously, with TAR DNA-binding protein 43 (TDP-43) dysfunction being linked to the underlying pathology of both diseases." (PMID 36835433, 2023).
essential tremor (1 paper, 2014). A relatively common disorder characterized by a fairly specific pattern of tremors which are most prominent in the upper extremities and neck, inducing titubations of the head. "We sequenced the exons coding the NES domains of five RNA-binding proteins (TARDBP, hnRNPA2B1, hnRNPA1, TAF15 and EWSR1) that have been previously implicated in neurodegeneration in a series of 257 essential tremor (ET) cases and 376 healthy controls." (PMID 25375143, 2014).
Genetic motor neuron disease (1 paper, 2022). "Mutations in the TARDBP gene are a rare cause of genetic motor neuron disease (MND)." (PMID 35911889, 2022).
myasthenia gravis (1 paper, 2021). Myasthenia gravis (MG) is a rare, clinically heterogeneous, autoimmune disorder of the neuromuscular junction characterized by fatigable weakness of voluntary muscles. "Importantly, these systems showed functional NMJ formation, measured skeletal fiber contractility, modeled axonal transport of pathophysiological TAR DNA binding protein 43 (TDP-43) in the case of ALS and could even induce a model of myasthenia gravis with patient-derived antibodies targeting NMJs." (PMID 33438114, 2021).
neuronal ceroid lipofuscinosis (1 paper, 2014). "With the respect to the GRN gene, a partial loss of function causes FTLD with ubiquitinated TAR DNA-binding protein-43-positive inclusions, while the complete loss of function develops neuronal ceroid lipofuscinosis." (PMID 25478031, 2014).
prostate tumor (1 paper, 2019). "Previous publications indicate that all four of the biomarkers tested in the current work (PAK7, TARDBP, TLN1 and CALD1) are highly expressed in prostate tumor cells as compared with non-cancerous prostate tissues." (PMID 31404106, 2019).
sarcoidosis (1 paper, 2020). Sarcoidosis is a multisystemic disorder of unknown cause characterized by the formation of immune granulomas in involved organs. "Surprisingly, we also identified an autoAb against TAR DNA-binding protein-43 (TDP-43), an ALS-associated gene, as a natural autoAb of sarcoidosis." (PMID 32046322, 2020).
neurodegenerative disease (817 papers, 2008 to 2026). A disorder of the central nervous system characterized by gradual and progressive loss of neural tissue and neurologic function. "Aggregation-prone proteins associated with neurodegenerative diseases, including TAR DNA-binding protein 43 (TDP-43) and α-synuclein, are degraded and/or suppressed by Praja1." (PMID 41182881, 2025). "Protein structural plasticity is a key hallmark of several proteins involved in neurodegenerative disease, including alpha-synuclein in PD, tau in AD, and TAR DNA-binding protein 43 (TDP-43) in ALS." (PMID 40544994, 2025). "For instance, protein inclusions containing TAR DNA-binding protein 43 (TDP-43) are a pathological hallmark of several neurodegenerative diseases, including the majority of ALS cases and significant subsets of FTD and AD cases." (PMID 39255192, 2024). "Some neurodegenerative diseases are associated with abnormal aggregation of TAR DNA binding protein-43 (TDP-43)." (PMID 38347544, 2024). "Deposits of aggregatedTAR DNA-binding protein 43 (TDP-43) in thebrain are associated with several neurodegenerative diseases." (PMID 39610319, 2024). "TAR DNA-binding protein-43 (TDP-43) accumulation is the primary pathology underlying several neurodegenerative diseases." (PMID 37150879, 2023). "The presence of inclusions containing phosphorylated TAR DNA-binding protein 43 (pTDP-43) is a hallmark of several neurodegenerative diseases." (PMID 35386195, 2022). "Behavioural Variant Frontotemporal Dementia (bvFTD) is a neurodegenerative disease characterized by the pathological accumulation of proteins including tau, TAR DNA-binding protein 43 (TDP-43) and fused in sarcoma (FUS) protein amongst others." (PMID 36340772, 2022). "Two of the most frequently observed proteins that comprise pathological inclusions in a broad range of neurodegenerative diseases are TAR-DNA binding protein of 43 kDa (TDP-43) and microtubule associated protein tau (tau)." (PMID 31703746, 2019). "These two neurodegenerative diseases have a common pathological background caused by the abnormal accumulation of TAR DNA-binding protein 43 (TDP-43)." (PMID 29449800, 2018). "Tar-DNA binding protein-43 is a ubiquitously expressed RNA-binding protein strongly linked to several neurodegenerative diseases." (PMID 25806046, 2015). "TAR DNA binding protein 43 (TDP-43) has recently been implicated in multiple neurodegenerative diseases." (PMID 26571498, 2015). "TAR DNA-binding protein 43 (TDP-43) is an RBP associated with neurodegenerative diseases." (PMID 40271197, 2025). "TAR DNA-binding Protein 43 (TDP-43) is linked to the pathology of neurodegenerative diseases." (PMID 41040969, 2025). "In addition, it has been shown that phosphorylation of SQSTM1 is closely associated with cisplatin resistance in tumor cells and the progression of the TAR DNA binding protein (TARDBP) associated neurodegenerative diseases." (PMID 39621600, 2024). "At first, the molecular mechanisms underlying neurodegenerative diseases were largely focused on gross anatomical changes, including protein aggregation (e.g., amyloid beta (Aβ), neurofibrillary tangles (NFTs), TAR DNA binding protein 43 (TDP-43)) and neuronal damage." (PMID 37433768, 2023). "In this study, we report the identification and functional analyses of two novel and one known mutation in TARDBP that we identified as a result of extensive mutation analyses in a cohort of 296 patients with variable neurodegenerative diseases associated with TDP-43 histopathology." (PMID 18802454, 2008). "In the context of neurodegenerative diseases, proteostasis loss substentially contributes to the abnormal accumulation of various pathological proteins, including amyloid-beta (Aβ), hyperphosphorylated tau, α-synuclein (α-syn), TAR DNA binding protein-43 (TDP-43), huntingtin (HTT)." (PMID 40059211, 2025).
neurodegenerative disease (continued). "Because several human proteins associated with neurodegenerative diseases, such as synuclein alpha and TARDBP, were found to form cytoplasmic aggregates in yeast in previous studies, we hypothesized that the toxicity of the 20 human genes was linked to the formation of protein aggregates in yeast." (PMID 28596290, 2017). "TAR DNA-binding protein 43 (TDP-43) undergoes hyperphosphorylation and cytoplasmic aggregation in various neurodegenerative diseases." (PMID 41602984, 2026). "TAR DNA-binding protein (TDP-43) has been identified as a major pathological protein in several neurodegenerative diseases." (PMID 41939353, 2026). "Pathogenic mutations in the TDP-43 gene, TARDBP, that promote filament formation have established a causal role for TDP-43 assembly in neurodegenerative diseases." (PMID 41659424, 2026). "Neurodegenerative diseases accumulate different protein aggregates in the brain, such as amyloid, tau, α-synuclein (a-syn) or TAR DNA-binding protein 43,27-31 though very often different protein aggregates are present within the same individual." (PMID 39974178, 2025). "ALS was among the first neurodegenerative diseases where Golgi fragmentation was described, an observation consistently found across all patients and animal models linked to mutations in SOD1, TARDBP (TDP-43), VAPB, and C9Orf72." (PMID 40552310, 2025). "Increased phosphorylation and mislocalization of TAR DNA-binding protein 43 (TDP-43) are detected in a group of neurodegenerative diseases including ALS, FTD, HD, and AD." (PMID 41204969, 2025). "They showed that TAR DNA-binding protein 43 (TDP-43), which is involved in neurodegenerative diseases, promotes the expression of NEAT1 by modulating the TIRR/53BP1 complex." (PMID 40362651, 2025). "Neurodegenerative diseases are characterized by the accumulation of misfolded proteins and influenced by genetic risk factors (e.g., APOE4, TARDBP)." (PMID 40558545, 2025). "TAR DNA-binding proteinwith 43 kD (TDP-43) is a partially disorderedprotein that misfolds and accumulates in the brains of patients affectedby several neurodegenerative diseases." (PMID 38116987, 2024). "Pathologic aggregates of TAR DNA-binding protein 43 kDa (TDP-43) is a common neuropathological finding observed in many neurodegenerative diseases." (PMID 38308693, 2024). "This letter demonstrates the potential of novel cryptic proteins resulting from TAR DNA-binding protein 43 (TDP-43) dysfunction as markers of TDP-43 pathology in neurodegenerative diseases." (PMID 38539264, 2024). "TARDBP (TAR DNA Binding Protein) and FUS (FUS RNA Binding Protein) are mRNA binding proteins linked to neurodegenerative diseases." (PMID 38255791, 2024). "Autophagy plays a crucial role in eliminating aggregated proteins implicated in various neurodegenerative diseases, such as mutant α-synuclein in PD, mutant huntingtin in HD, and mutant TAR DNA-binding protein 43 (TDP-43) in ALS." (PMID 39411483, 2024). "A vast number of studies have shown that soluble oligomers of amyloid-β, α-synuclein, tau, and TDP-43 (TAR DNA-binding protein 43) are the toxic species that appear before disease onset and are one of the main drivers of other neurodegenerative diseases." (PMID 38295729, 2024). "Mutations in these genes directly increase protein aggregation, a key hallmark of all neurodegenerative diseases, with TAR DNA-binding protein 43 (TDP-43) aggregates found in > 95% of ALS patients." (PMID 37481656, 2023). "Mutations in the SNCA, TARDBP and MAPT genes that alter specific amino acids also increase the risk for neurodegenerative disease and are thought to do so by increasing the rate of protein self-association." (PMID 37131250, 2023). "This pathway was further shown to promote degradation of a broad range of pathogenic proteins associated with multiple neurodegenerative diseases, including Ataxin-1, huntingtin, and TAR DNA-binding protein 43 (TDP-43)." (PMID 38201212, 2023).